BOK (BCL2 family apoptosis regulator BOK)
Description:
[Isoform 1]: Apoptosis regulator that functions through different apoptotic signaling pathways. Plays a roles as pro-apoptotic protein that positively regulates intrinsic apoptotic process in a BAX- and BAK1-dependent manner or in a BAX- and BAK1-independent manner. In response to endoplasmic reticulum stress promotes mitochondrial apoptosis through downstream BAX/BAK1 activation and positive regulation of PERK-mediated unfolded protein response (By similarity). Activates apoptosis independently of heterodimerization with survival-promoting BCL2 and BCL2L1 through induction of mitochondrial outer membrane permeabilization, in a BAX- and BAK1-independent manner, in response to inhibition of ERAD-proteasome degradation system, resulting in cytochrome c release. Plays a role in granulosa cell apoptosis by CASP3 activation. Plays a roles as anti-apoptotic protein during neuronal apoptotic process, by negatively regulating poly ADP-ribose polymerase-dependent cell death through regulation of neuronal calcium homeostasis and mitochondrial bioenergetics in response to NMDA excitation (By similarity). In addition to its role in apoptosis, may regulate trophoblast cell proliferation during the early stages of placental development, by acting on G1/S transition through regulation of CCNE1 expression. May also play a role as an inducer of autophagy by disrupting interaction between MCL1 and BECN1. [Isoform 2]: Pro-apoptotic molecule exerting its function through the mitochondrial pathway.
Synonyms: BCL2L9; BOKL; MGC4631
Tractability: Antibody: UniProt predicts a signal peptide or a membrane-spanning region. PROTAC: UniProt records ubiquitination sites on it; ubiquitination databases record sites on it; its protein half-life has been measured.
Gene: Protein-coding gene on chromosome 2 (241,551,300 to 241,574,568, forward strand). Ensembl gene ENSG00000176720.
Subcellular location: Mitochondrion membrane (Isoform 1); Endoplasmic reticulum membrane; Mitochondrion inner membrane; Cytoplasm; Nucleus; Mitochondrion; Endoplasmic reticulum; Mitochondrion outer membrane; Early endosome membrane; Recycling endosome membrane; Nucleus outer membrane; Golgi apparatus, cis-Golgi network membrane; Golgi apparatus, trans-Golgi network membrane; Membrane; Membrane (Isoform 2)
Gene Ontology:
Molecular function: protein binding; channel activity; protein heterodimerization activity; protein homodimerization activity; BH domain binding; protein dimerization activity; protein-containing complex binding; signaling receptor binding; ubiquitin protein ligase binding
Biological process: apoptotic process; positive regulation of apoptotic process; positive regulation of execution phase of apoptosis; regulation of autophagy; regulation of chorionic trophoblast cell proliferation; regulation of granulosa cell apoptotic process; release of cytochrome c from mitochondria; cellular component disassembly involved in execution phase of apoptosis; extrinsic apoptotic signaling pathway in absence of ligand; intrinsic apoptotic signaling pathway in response to DNA damage; negative regulation of apoptotic process; positive regulation of endoplasmic reticulum stress-induced intrinsic apoptotic signaling pathway; positive regulation of intrinsic apoptotic signaling pathway; positive regulation of mitochondrial outer membrane permeabilization involved in apoptotic signaling pathway; positive regulation of PERK-mediated unfolded protein response; protein complex oligomerization; male gonad development; negative regulation of mitochondrial depolarization; negative regulation of mitochondrial outer membrane permeabilization involved in apoptotic signaling pathway; negative regulation of necroptotic process; negative regulation of neuron apoptotic process; oligodendrocyte differentiation; regulation of apoptotic process; regulation of cytosolic calcium ion concentration; and 2 more
Cellular component: cytoplasm; endoplasmic reticulum; endoplasmic reticulum membrane; Golgi apparatus; membrane; mitochondrial inner membrane; mitochondrial membrane; mitochondrial outer membrane; mitochondrion; nucleus; cis-Golgi network membrane; early endosome membrane; recycling endosome membrane; trans-Golgi network membrane; nuclear outer membrane
Genetic constraint (gnomAD): Loss-of-function variants: 20 observed, 15.24 expected, observed/expected ratio (o/e) 1.31, 90% interval 0.92 to 1.82. The synonymous counts are far from expectation, so gnomAD's model fits this gene poorly and the ratio says little. Missense variants: 348 observed, 252.17 expected, observed/expected ratio (o/e) 1.38, 90% interval 1.26 to 1.51. Synonymous variants: 173 observed, 120 expected, observed/expected ratio (o/e) 1.44, 90% interval 1.27 to 1.63.
Homologues: Orthologues: macaque BOK (100% identical), chimpanzee BOK (96% identical), mouse Bok (96% identical), rat Bok (96% identical), pig BOK (92% identical), dog BOK (78% identical), tropical clawed frog bok (70% identical), guinea pig BOK (68% identical), zebrafish boka (67% identical), zebrafish bokb (56% identical), Drosophila melanogaster Debcl (32% identical), Drosophila melanogaster Buffy (31% identical). Paralogues in human: MCL1 (22% identical), BCL2 (21% identical), BCL2L1 (20% identical), BCL2L10 (20% identical), BAK1 (19% identical), BAX (19% identical), BCL2L2 (18% identical), BCL2A1 (15% identical).
Diseases named in the same sentence as BOK in open-access papers:
BOK is named in the same sentence as 36 diseases in open-access papers, as found by Europe PMC text mining. Sharing a sentence is not in itself a finding about the gene and the disease. The quoted sentences say what the papers report.
colorectal cancer (9 papers, 2018 to 2025). A primary or metastatic malignant neoplasm that affects the colon or rectum. "They found that patients with stage II/III colorectal cancer showed a decreased level of BOK, but increased BOK level was associated with reduced overall survival time." (PMID 35387121, 2022). "Studies have demonstrated that BOK is downregulated in early non-small cell lung cancer and colorectal cancer and has potential prognostic value." (PMID 40806384, 2025). "BOK can serve as a prognostic marker for colorectal cancer, and it has been suggested that different levels of BOK activity drives the progression of cancer." (PMID 33216728, 2020). "In colorectal carcinoma tissue, in which BOK protein was also found to be decreased compared to matched healthy tissue, promoter hypomethylation rather than hypermethylation has been observed, thus excluding epigenetic downregulation in CRC." (PMID 33043006, 2020). "In this study, we showed that stage II and III colorectal cancer patients possessed decreased levels of BOK protein in their tumours compared to matched normal tissue." (PMID 29374142, 2018). "Numerous studies have demonstrated BOK involvement in the pathogenesis of various cancer types, indicating its potential anti-cancer effects in breast, liver, non-small cell lung, and colorectal cancers." (PMID 40806384, 2025). "Additionally, disruption of WNT signaling significantly decreased BOK expression in the colorectal cancer cell line Ls174T, indicating that Wnt signaling controls the expression of pro-apoptotic BOK." (PMID 40806384, 2025). "So, the BOK gene is studied as a prognostic marker in colorectal cancer." (PMID 37994325, 2023). "Thus, delete of BOK was usually found in tumors, including breast cancer, non-small cell lung carcinoma and colorectal cancer." (PMID 35387121, 2022). "Furthermore, the proliferative defect seen after downregulation of BOK in human HCT-116 colorectal carcinoma cells is dependent on increased cell cycle arrest, due to the higher levels of the cyclin kinase inhibitors p19INK4d and p21cip1." (PMID 35091677, 2022).
breast carcinoma (6 papers, 2017 to 2025). "Overexpression of BAK1 has previously been associated with a favourable prognosis in breast cancer, while BOK, BAK1 and HRK as effectors are inserted into the mitochondrial outer membrane, resulting in MOMP without sequestration by the guardians." (PMID 32419250, 2020). "Furthermore, this study contributed to an enhanced comprehension of the mechanisms underlying breast cancer metastasis and proposed BOK as a promising prognostic marker and therapeutic target for breast cancer." (PMID 40806384, 2025). "Subsequently, the migration of two breast cancer cells was detected using wound healing and Transwell migration assays after BOK overexpression." (PMID 40806384, 2025). "The results revealed that BOK was significantly downregulated in 1085 cases of breast cancer tissues compared to 291 normal tissues." (PMID 40806384, 2025). "This study first explored BOK expression in normal populations and patients with breast cancer and the correlation between the BOK expression level and overall survival based on the database." (PMID 40806384, 2025). "Additional studies revealed that BOK silencing promoted the expression of EMT-related markers in breast cancer cells, while BOK overexpression inhibited EMT and migration." (PMID 40806384, 2025). "In this present study, BOK underwent ubiquitin-mediated degradation in breast cancer cells, and MG132 has been shown to inhibit the EMT process and the migration of MCF-7 cells." (PMID 40806384, 2025). "Using RNA-seq sequencing and Western blotting, we confirmed that the Wnt signaling pathway is involved in BOK regulating the EMT process in breast cancer cells." (PMID 40806384, 2025). "This study demonstrated that BOK undergoes ubiquitination-mediated degradation in breast cancer cells and that MG132 inhibits the EMT process and migration ability in MCF-7 cells." (PMID 40806384, 2025). "The experimental results further support that BOK suppresses the EMT process in breast cancer cells." (PMID 40806384, 2025). "Like in NSCLC, BOK protein levels were again found to be significantly lower in tumor tissue compared to matched normal tissue, and higher BOK expression positively correlated with overall as well as with relapse-free survival of breast cancer patients." (PMID 33043006, 2020). "At the level of mRNA stability and translation, BOK was found to be downregulated by binding of the miRNA miR-296-5p to its 3’ UTR in breast cancer cells." (PMID 33043006, 2020). "Here, we discovered that miR-296-5p regulates BOK expression by binding to its 3’-UTR in breast cancers." (PMID 29156771, 2017). "To substantiate this notion, we tested the expression of other pro- and anti-apoptotic members of Bcl-2 family in BOK/Mcl-1 silenced breast cancer cells." (PMID 29156771, 2017). "We chose to use MDA-MB-231 and MDA-MB-468 cells for determining miR-296-5p function as well as regulation of BOK and Mcl-1 as these cell lines have lower levels of miR-296-5p and higher levels of BOK and Mcl-1 compared to other breast cancer cell lines." (PMID 29156771, 2017). "Supporting this, we identified several potential GSK3 phosphorylation sites on BOK protein and showed that the inhibition of GSK3α/β led to increased expression of BOK in breast cancer cells." (PMID 29156771, 2017). "To begin to address the importance of BOK in cancers, we first investigated BOK expression levels in breast cancers." (PMID 29156771, 2017). "Overexpression of miR-296-5p resulted in significantly decreased BOK mRNA and protein levels in breast cancer cells compared to mock or untransfected controls." (PMID 29156771, 2017). "Our results reveal that BOK expression in breast cancer is regulated at the post-transcriptional as well as post-translational levels." (PMID 29156771, 2017). "To further substantiate these results, we performed annexin V-FITC/PI staining on miR-296-5p or BOK siRNA transfected breast cancer cells." (PMID 29156771, 2017).
breast carcinoma (continued). "Our results reveal that Mcl-1 and BOK constitute a regulatory feedback loop as ectopic BOK expression induces Mcl-1, whereas silencing of Mcl-1 results in reduced BOK levels in breast cancer cells." (PMID 29156771, 2017). "Before we addressed miR-296-5p-dependent regulation of BOK, we determined the role of miR-296-5p in breast cancer." (PMID 29156771, 2017). "Pharmacological inhibition of GSK3 with CHIR99021 or silencing of GSK3α/β using siRNAs resulted in elevated BOK protein levels in breast cancer cells." (PMID 29156771, 2017). "To understand the functional relevance of the cross-talk between pro- and anti-apoptotic proteins, we performed long-term viability assay in breast cancer cells depleted for both BOK/Mcl-1." (PMID 29156771, 2017). "Silencing of both Mcl-1 and BOK rescued the effect of Mcl-1 silencing on breast cancer cell growth, suggesting that BOK is important for attenuating cell growth in the absence of Mcl-1." (PMID 29156771, 2017). "Kaplan-Meir analysis revealed that higher BOK expression positively correlated with overall survival as well as relapse free survival of breast cancer patients." (PMID 29156771, 2017). "Moreover, using the GEPIA and Kaplan–Meier plotter database analyses, we found that BOK is lowly expressed in patients with breast cancer, and patients with high BOK expression exhibit longer survival times and increased survival probabilities." (PMID 40806384, 2025). "Although BOK is involved in the development of various types of cancer, its mechanism of action in breast cancer remains unclear." (PMID 40806384, 2025). "As demonstrated by our study, BOK plays an inhibitory role in breast cancer progression." (PMID 40806384, 2025). "This study enhances our understanding of breast cancer pathogenesis and suggests that BOK may serve as a potential prognostic marker and therapeutic target for breast cancer." (PMID 40806384, 2025). "This study demonstrated that BOK suppresses the migration of breast cancer cells by inhibiting EMT." (PMID 40806384, 2025). "Furthermore, interfering BOK reversed the inhibition of breast cancer cell migration and the EMT process by MG132." (PMID 40806384, 2025). "Therefore, we conclude that low BOK expression promotes breast cancer EMT and migration by activating the Wnt signaling pathway." (PMID 40806384, 2025). "This provides new insights into the role of BOK in developing breast cancer." (PMID 40806384, 2025). "However, the detailed mechanism by which BOK regulates the Wnt signaling pathway during the EMT process in breast cancer cells still needs further investigation." (PMID 40806384, 2025). "This suggests that BOK is a promising prognostic marker and therapeutic target for breast cancer." (PMID 40806384, 2025). "Besides NSCLC and breast cancer, BOK has been shown to be downregulated in CRC and to be of potential prognostic and predictive value, respectively." (PMID 33043006, 2020). "This study also describes an miR-296-5p–mediated regulatory feedback loop between MCL-1 and BOK levels that determines whether the breast cancer cells die by apoptosis or survive." (PMID 33043006, 2020). "Furthermore, we demonstrate that glycogen synthase kinase (GSK3) α/β interacts with BOK and regulates its level post-translationally in breast cancer cells." (PMID 29156771, 2017). "Next, we assessed whether the compensatory effects of BOK and Mcl-1 silencing on breast cancer growth has similar effect on apoptosis." (PMID 29156771, 2017). "Indeed, ectopic expression of BOK induced Mcl-1 expression, while silencing of Mcl-1 resulted in reduced expression of BOK in breast cancer cells." (PMID 29156771, 2017). "Indeed, levels of several pro-survival proteins were found to be elevated when breast cancer cells were depleted for both Mcl-1 and BOK compared to silencing of either of them alone." (PMID 29156771, 2017).
breast carcinoma (continued). "Furthermore, in the presence of paclitaxel treatment, miR-296-5p and BOK silencing suppressed paclitaxel-induced apoptosis compared to scramble transfected breast cancer cells treated with paclitaxel." (PMID 29156771, 2017). "It is possible that differential regulation of BOK and Mcl-1 by miR-296-5p may determine whether pro- or anti-apoptotic functions prevail and accordingly affect the survival of breast cancer patients." (PMID 29156771, 2017). "Our results showing rescue of growth inhibitory effect of Mcl-1 knockdown in BOK and Mcl-1 depleted breast cancer cells suggest that BOK and Mcl-1 may be in a complimentary feedback loop." (PMID 29156771, 2017). "Having shown that BOK is a critical regulator that plays an important role in determining whether cancer cells die or survive, we wondered whether there are other means by which BOK expression may be regulated in breast cancers." (PMID 29156771, 2017). "In this report, we address the regulation of pro-apoptotic protein BOK in breast cancers." (PMID 29156771, 2017). "Next, we addressed the clinical significance of lower BOK expression in breast cancers." (PMID 29156771, 2017). "We demonstrated for the first time that BOK is regulated by miR-296-5p in breast cancers." (PMID 29156771, 2017). "Since miRNAs have been shown to regulate the expression of several genes involved in apoptosis, we predicted that miRNAs might play important role in regulating BOK expression in breast cancer." (PMID 29156771, 2017). "Notably, breast cancer cells transfected with either miR-296-5p or siRNA against BOK led to significant suppression of activated caspase-3 level in the presence of paclitaxel compared to vehicle treatment." (PMID 29156771, 2017). "Here, we evaluated whether BOK-Mcl-1 interaction affected their levels and respective functions in breast cancers." (PMID 29156771, 2017). "In addition to miR-296-5p, we demonstrate that glycogen synthase kinases 3 α/β (GSK3α/β) regulate BOK expression by physically interacting with BOK in breast cancer cells." (PMID 29156771, 2017). "Therefore, we propose the hypothesis that BOK plays a role in inhibiting metastasis in breast cancer." (PMID 40806384, 2025). "To further investigate the mechanism by which low BOK expression promotes the EMT and migration ability of breast cancer cells, we found that the differentially expressed genes were significantly enriched in the Wnt signaling pathway." (PMID 40806384, 2025). "Next, we checked expression levels of the effectors BOK, BAX, and anti-apoptotic BCL-2 family members in LUAD, LUSC, and breast cancer (BRCA)." (PMID 39996719, 2025). "It then assessed breast cancer cell migration and EMT occurrence following BOK upregulation or downregulation." (PMID 40806384, 2025). "This study found that BOK was involved in the process of MG132, inhibiting the migration and epithelial–mesenchymal transition (EMT) of breast cancer cells induced by transforming growth factor-β." (PMID 40806384, 2025). "However, BOK knockdown can reverse these phenomena, confirming that BOK ubiquitination-mediated degradation is involved in the EMT process and migration of breast cancer cells." (PMID 40806384, 2025). "As a result, BOK may play a key role in regulating the EMT process and impacting the progression of breast cancer cells." (PMID 40806384, 2025). "In conclusion, low expression of BOK may contribute to the activation of the Wnt signaling pathway, which in turn mediates the epithelial–mesenchymal transition (EMT) process in breast cancer cells and enhances their migratory capacity." (PMID 40806384, 2025). "Next, we tested whether BOK is indeed a bonafide target of miR-296-5p by assessing BOK levels in MDA-MB-231 and MDA-MB-468 breast cancer cells, ectopically expressing miR-296-5p or anti-miR-296-5p (miR-296-5p inhibitor)." (PMID 29156771, 2017). "Therefore, the ubiquitination of BOK may play a role in the EMT process and the migration of breast cancer cells." (PMID 40806384, 2025).